PHGR1 (proline, histidine and glycine rich 1)
Tractability: No criterion of Open Targets' tractability assessment is met for any kind of drug.
Gene: Protein-coding gene on chromosome 15 (40,351,033 to 40,356,434, forward strand). Ensembl gene ENSG00000233041.
Subcellular location (Human Protein Atlas): Vesicles
Genetic constraint (gnomAD): Loss-of-function variants: 3 observed, 5.22 expected, observed/expected ratio (o/e) 0.57, 90% interval 0.26 to 1.45. That is too few expected variants to judge how well the gene tolerates losing a copy. Missense variants: 81 observed, 117.04 expected, observed/expected ratio (o/e) 0.69, 90% interval 0.58 to 0.83. Synonymous variants: 32 observed, 44.12 expected, observed/expected ratio (o/e) 0.73, 90% interval 0.55 to 0.97.
Homologues: Orthologues: chimpanzee PHGR1 (100% identical), macaque PHGR1 (94% identical), rabbit PHGR1 (65% identical).
Diseases named in the same sentence as PHGR1 in open-access papers:
PHGR1 is named in the same sentence as 9 diseases in open-access papers, as found by Europe PMC text mining. Sharing a sentence is not in itself a finding about the gene and the disease. The quoted sentences say what the papers report.
colorectal cancer (4 papers, 2018 to 2025). A primary or metastatic malignant neoplasm that affects the colon or rectum. "Diverticulitis of the colon is primarily linked to proline, histidine and glycine rich 1 (PHGR1), which may present either independently or as a complication of colorectal cancer." (PMID 40608007, 2025). "The second transcript was PHGR1 which has been reported to play an essential role in gastrointestinal epithelium and has demonstrated potentials for clinical application in colorectal cancer lymph node metastases detection." (PMID 31737124, 2019). "Functional analyses of the novel PHGR1 mRNA and protein suggest an essential role in gastrointestinal epithelium and a clinical application in detection of colorectal cancer lymph node metastases." (PMID 29415677, 2018). "Here, we describe the first molecular characterization of PHGR1 and suggest a clinical utility in colorectal cancer diagnostics." (PMID 29415677, 2018). "All examined lymph nodes (n = 4) were clearly positive for PHGR1 in the metastatic areas, suggesting that the PHGR1 protein is a potential marker of lymph node metastasis in colorectal cancer." (PMID 29415677, 2018). "We also expect medical researchers to explore the biomarker potential of PHGR1 in clinical studies, notably with regard to colorectal cancer." (PMID 29415677, 2018). "Through bioinformatic searches for colorectal cancer biomarkers, we identified the novel gastrointestinal-specific proline-, histidine-, glycine-rich protein 1 (PHGR1)." (PMID 29415677, 2018). "Northern blotting revealed a single PHGR1 mRNA variant of approximately 490 bases in normal colonic mucosa, a colorectal tumor biopsy, and the colorectal cancer cell line LS174T (data not shown)." (PMID 29415677, 2018). "Examination of PHGR1 mRNA and protein levels in lymph nodes with known colorectal cancer metastases indicated that they may serve as biomarkers for detection of such metastases." (PMID 29415677, 2018). "Finally, we obtained evidence that both PHGR1 mRNA and protein may be promising biomarkers for the detection of metastases in colorectal cancer, as they have superior characteristics compared to the established metastasis marker KRT20." (PMID 29415677, 2018). "Finally, we demonstrated that PHGR1 mRNA and protein could be promising biomarkers for the detection of lymph node metastases in colorectal cancer patients." (PMID 29415677, 2018). "We hypothesized that PHGR1 may serve as a clinically useful biomarker for detection of lymph node metastasis in colorectal cancer patients because of our observation that PHGR1 mRNA levels are high in normal colon mucosa and very low in normal lymph nodes and several other tissues." (PMID 29415677, 2018). "For lymphatic cells, upregulation of PHGR1 and TFF3 was observed, which is essential for the invasion and metastasis of colorectal cancer." (PMID 38778448, 2024). "Therefore, high expression levels of PHGR1 should not be interpreted as a definitive marker for colorectal cancer, but they may serve as supplementary reference indicators." (PMID 40608007, 2025). "On Western blots using a polyclonal antibody against PHGR1 the LS174T, HT29, and HCT116 colorectal cancer cell lines and normal mucosa samples did not have a protein band around the expected molecular weight for PHGR1 (7.7 kDa)." (PMID 29415677, 2018).
colon cancer (1 paper, 2018). "On average, PHGR1 mRNA levels were 3.4 x 105 times higher in colon tumors than normal lymph nodes, whereas KRT20 mRNA levels were 1.3 × 105 times higher (P = 0.02)." (PMID 29415677, 2018). "The mean PHGR1 and KRT20 mRNA levels in examined colon cancers were 620- and 90-times higher than the mean level in the other tumor types tested (P < 0.001), respectively, indicating that PHGR1 is also more colon cancer-specific than KRT20." (PMID 29415677, 2018). "To compare PHGR1 and KRT20 in this context, we measured PHGR1 and KRT20 mRNA levels in tumor biopsies from 209 patients with operable colon cancer and normal mucosa biopsies from 76 of the 209 patients." (PMID 29415677, 2018). "To elucidate the functional pathways related to PHGR1 expression, we investigated the global transcriptional effects of PHGR1 knockdown in HT29 colon cancer cells." (PMID 29415677, 2018).
diverticulitis (1 paper, 2024). An infection that develops in the diverticula of the intestinal tract. "The relative genetic risk of 27 replicating loci in a European cohort identified that PHGR1, FAM155A-2, CALCB and S100A10 had a stronger effect in patients with diverticulitis as opposed to diverticulosis." (PMID 38831715, 2024).
gastric cancer (1 paper, 2023). A primary or metastatic malignant neoplasm involving the stomach. "Finally, we identified a gene set associated with the differentiation status of gastric cancer, including AGR3, CLDN3, CLDN4, FABP1, LGALS4, PHGR1, MYH14 and S100A14." (PMID 36729271, 2023).
cancer (4 papers, 2018 to 2026). A tumor composed of atypical neoplastic, often pleomorphic cells that invade other tissues. "Survival analyses across multiple cancer types confirmed the prognostic relevance of resistance-associated genes, including SPINK1, PHGR1, and APOD." (PMID 41724379, 2026). "The HT29 cancer cell line was chosen because of its moderately high PHGR1 mRNA levels in growing cultures." (PMID 29415677, 2018). "Not surprisingly, similarity among different cancer types was identified in only 6 out of 23 clusters, including E3 (IRS2, KRT6A), E5 (CD24, STMN1), E8 (GKN1, MUC5AC), E9 (PHGR1, TFF3), E10 (TFF3, TPO) and E13 (VTN and ITIH5)." (PMID 36333338, 2022).
tumor (4 papers, 2018 to 2025). "Eleven DEGs were observed between tumor and adjacent normal tissue including S100P, PHGR1 and S100A6." (PMID 36253784, 2022). "PHGR1, involved in ribosome biosynthesis, could potentially affect tumor growth and spread." (PMID 37702857, 2023). "Differentiation markers (e.g. KRT20 and PHGR1) can be used to detect small deposits of tumor cells in clinical samples normally negative for such markers, such as lymph nodes from resection specimens." (PMID 29415677, 2018).
PHGR1 also shares sentences with these, for which no sentence is quoted: diverticular disease of the colon (2 papers); lymph node metastases (2); colorectal tumor (1).